PHGDH (phosphoglycerate dehydrogenase)
Diseases named in the same sentence as PHGDH in open-access papers (continued):
Sharing a sentence is not in itself a finding about the gene and the disease.
lactic acidosis (1 paper, 2024). Metabolic acidosis characterized by the accumulation of lactate in the body. "Further support for our hypothesis of a disturbed NAD+/NADH ratios under lactic acidosis comes from altered mRNA expression of NAD+ consuming enzymes, such as phosphoglycerate dehydrogenase (PHGDH) and sirtuin-1 (SIRT-1)." (PMID 38195466, 2024).
liver diseases (1 paper, 2021). "Thus, more experimental studies are merited to further elucidate in what way epigenetic modification of PHGDH and SLC7A11 could explain the beneficial effect of coffee consumption on lipid metabolism and liver diseases." (PMID 33990564, 2021).
liver fibrosis (1 paper, 2025). "Sirius Red staining indicated that PHGDH knockout greatly enhanced DDC-promoted liver fibrosis." (PMID 39962071, 2025).
metastatic prostate carcinoma (1 paper, 2025). A carcinoma that arises from the prostate gland and has spread to other anatomic sites. "Notably, while PSAT1 and PSPH exhibited no change in expression by PLK1, PHGDH showed a significant decrease in our experimental models of advanced metastatic prostate cancers." (PMID 40475404, 2025).
pancreatic adenocarcinoma (1 paper, 2019). "The pancreatic adenocarcinoma patients with low PHGDH expression had better overall survival." (PMID 30744688, 2019). "The expressions of PHGDH were determined in cells and pancreatic adenocarcinomas." (PMID 30744688, 2019). "Moreover, PHGDH was also found to highly express in patient samples and positively related with the tumor malignancy, suggesting this metabolic preference was exploited in clinical pancreatic adenocarcinomas." (PMID 30744688, 2019). "Combining with clinical data, we analyzed the mRNA expression levels of PHGDH and SHMT1 in clinical samples from The Cancer Genome Atlas (TCGA) pancreatic adenocarcinoma cohort." (PMID 30744688, 2019).
PHGDH deficiency (1 paper, 2024). "Furthermore, it is plausible that a patient diagnosed with EIEE1 may also have an undetected second diagnosis of 3‐PHGDH deficiency due to underlying PHGDH mutations." (PMID 38400608, 2024).
phyllodes tumor (1 paper, 2018). A benign, borderline, or malignant fibroepithelial neoplasm arising from the breast and rarely the prostate gland. "The expression of serine–glycine biosynthetic genes including PHGDH, PSAT1 and GLDC is correlated to tumor grade and shorter disease-free survival in patients with phyllodes tumor." (PMID 29911072, 2018).
postmenopausal osteoporosis (1 paper, 2024). Metabolic disorder associated with fractures of the femoral neck, vertebrae, and distal forearm. "In addition, pharmacological phosphoglycerate dehydrogenase inhibition abrogated bone loss in a mouse model of postmenopausal osteoporosis by blocking bone resorption." (PMID 38200114, 2024).
progeria (1 paper, 2023). "Moreover, this axis also exists during ageing as the levels of PHGDH, PKM2 and H3pT11 are reduced in aged and progeria mice." (PMID 36899022, 2023).
prostate tumor (1 paper, 2025). "Collectively, this study demonstrates that the oncogenic PLK1 inhibits PHGDH, and subsequently compensatory serine uptake and changes in sphingolipid metabolism ultimately drive the cellular proliferation and prostate tumor growth." (PMID 40475404, 2025).
retinal degeneration (1 paper, 2021). Degeneration of the retina. "PHGDH is strongly expressed in the liver, the major tissue responsible for production of the deoxysphingolipids associated with retinal degeneration in serine-deprived animal models of MacTel8." (PMID 33654266, 2021).
steatosis (1 paper, 2022). Increased lipid within the cytoplasm of cells. "For example, decreased hepatic PHGDH level has been found in the HFD- or MCD-induced steatosis animals, and in patients of alcoholic and non-alcoholic liver diseases, which is associated with lower hepatic serine levels." (PMID 35788583, 2022).
Stroke (1 paper, 2025). Sudden impairment of blood flow to a part of the brain due to occlusion or rupture of an artery to the brain. "Results revealed significantly higher mNSS scores in the AAV9-GFAP-siPHGDH group post-MCAO, indicating that astrocyte-specific PHGDH knockdown exacerbated sensorimotor function impairment after stroke." (PMID 41344159, 2025).
teratocarcinoma (1 paper, 2018). A germ cell tumor characterized by the presence of an embryonal carcinoma component and a teratoma component. "Considering the clinically relevant link between PHGDH/Oct4 co-expression and patient survival, NT2/D1 teratocarcinoma cells with stem-like features will stimulate further research into the therapeutic utility of PHGDH–Oct4 axis." (PMID 30250195, 2018). "Therefore, to study the relationship between PHGDH and Oct4, we used a human teratocarcinoma cell line NT2/D1, which expresses high levels of pluripotency factor Oct422." (PMID 30250195, 2018).
urothelial carcinoma (1 paper, 2022). A malignant neoplasm derived from the transitional epithelium of the urinary tract (urinary bladder, ureter, urethra, or renal pelvis). "Both PHGDH and TRIM29 exhibited significant expression in SCC of the lung and urothelial carcinoma." (PMID 35204409, 2022).
varicocele (1 paper, 2020). A condition characterized by the dilated tortuous veins of the spermatic cord with a marked left-sided predominance. "Our study suggests that the decrease in glycolysis products due to low expression of PHGDH may also be an important cause of apoptosis in varicocele." (PMID 32664979, 2020). "We revealed that varicocele lead to the low expression of PHGDH in sertoli cells and the low expression of PHGDH ultimately led to a decrease in lactate production by affecting the glycolysis pathway." (PMID 32664979, 2020). "Experimental rat varicocele model was constructed according to our new clip technique, the mRNA and protein expression levels of PHGDH were examined with qRT-PCR and Western blotting." (PMID 32664979, 2020). "In summary, our current findings indicate that varicocele lead to the low expression of PHGDH in sertoli cells and the low expression of PHGDH ultimately led to a decrease in lactate production by affecting the glycolysis pathway." (PMID 32664979, 2020). "The results showed that testicular protein PHGDH was down-regulated in patients with varicocele and in experimental rat varicocele model." (PMID 32664979, 2020). "In this study, we collected the testicular tissue from patients with varicocele, the glycolysis related proteins PHGDH was identified by iTRAQ proteomics technology." (PMID 32664979, 2020). "In this study, We found for the first time that the lactate on the varicocele side of the patients decreased and testicular protein PHGDH was down-regulated in varicocele." (PMID 32664979, 2020). "To investigate the mechanism behind the reduction of lactate, we collected a small amount of testicular tissue from patients with varicocele and found that the glycolysis related proteins PHGDH was down-regulated in varicocele patients (Supplementary File1)." (PMID 32664979, 2020). "Notably, PHGDH mRNA and protein expression was obviously reduced in the left testes from the varicocele group relative to the sham group." (PMID 32664979, 2020). "Finally, we found that testicular protein PHGDH was down-regulated in varicocele patients and rat varicocele model, the decrease of PHGDH expression may be the reason for the decrease of lactate." (PMID 32664979, 2020).
cancer (284 papers, 2011 to 2026). A tumor composed of atypical neoplastic, often pleomorphic cells that invade other tissues. "These ISR-activated cancer cells exhibited broad chemoresistance and apoptosis resistance, yet were auxotrophic for serine due to loss of PHGDH and CBS expression, impairing serine and cysteine biosynthesis." (PMID 41704035, 2026). "High PHGDH expression is observed in various cancers and is associated with poor prognosis, including lower relapse-free and overall survival rates." (PMID 39934141, 2025). "Phosphoglycerate dehydrogenase (PHGDH), the first rate-limiting enzyme of serine synthesis, was overexpressed and associated with the development of cancers." (PMID 39990672, 2025). "Coherently many tumors upregulate the SSP mostly through PHGDH overexpression and PHGDH has been associated with poor prognosis in several types of cancers." (PMID 40640948, 2025). "The rate-limiting enzyme PHGDH plays a crucial role in serine synthesis and exhibits significant associations with various cancers." (PMID 38945960, 2024). "In cancer cells, knockdown of PHGDH that causes reduced serine synthesis also reduces central carbon metabolism." (PMID 37115691, 2023). "Although the mechanisms underlying PHGDH overexpression in cancer have been well illustrated, the role and regulatory mechanism of PHGDH activity in cancer remains poorly understood." (PMID 36823188, 2023). "PHGDH amplification is associated with oncogenesis, and PHGDH knockdown or silencing shows anti-cancer effects in vivo and in vitro." (PMID 37664062, 2023). "PHGDH has been reported to be involved in the progression of various cancers and associated with poor prognosis." (PMID 37387559, 2023). "Loss of PHGDH or direct blockage of serine biosynthesis via the pharmacological inhibition of PHGDH can inhibit cancer cell proliferation and attenuate tumor growth and metastasis." (PMID 38098117, 2023). "We specifically discuss the functions of the cancer-associated enzymes phosphoglycerate dehydrogenase and pyruvate kinase muscle 2 in skeletal muscle." (PMID 35460513, 2022). "Many reports have indicated that overexpression of PHGDH is associated with various diseases, especially cancer." (PMID 35365231, 2022). "It has also been demonstrated that the dependence of cancer cells on serine can result from the amplification of the serine synthesis pathway enzymes especially PHGDH encoded by the gene located in chromosome 1p." (PMID 35216362, 2022). "PHGDH is frequently overexpressed in multiple human cancers and is associated with poor prognosis in cancer patients." (PMID 34957102, 2021). "3-phosphoglycerate dehydrogenase (PHGDH) expression in cancer has been linked to shorter progression-free survival, increased rates of metastasis, and poorer overall survival." (PMID 33511334, 2020). "While some metabolic enzyme copy number variants (CNV) such as PHGDH amplification have been associated with cancer, the link between CNV and its impact on cancer metabolism is still unclear." (PMID 32411371, 2020). "The overexpression of PHGDH is often associated with progression of cancers, and the inhibitors of PHGDH reduce the glycolysis and suppress the growth of cancers." (PMID 32664979, 2020). "Overactive MEK/ERK signalling in BRAF- and NRAS-mutated cancers can overexpress PHGDH through ATF4 activation, driving utilization of the serine synthesis pathway to generate glutathione as a resistance mechanism." (PMID 33511334, 2020). "These patient-derived tumor datasets further supported our in vitro findings regarding the association between the serine-metabolizing enzyme PHGDH and the cancer stemness-maintaining factors." (PMID 30250195, 2018).
cancer (continued). "High levels of PHGDH have been associated with enhanced proliferation and poor prognosis in various types of cancers, and cancer cells that harbor high levels of PHGDH have been shown to be more susceptible to PHGDH inhibition." (PMID 30250195, 2018). "The gene encoding the serine biosynthesis pathway enzyme PHGDH is located in a region of focal genomic copy number gain in human cancers." (PMID 25926973, 2015). "Recently, by taking advantage of in vivo RNA interference (RNAi)-based loss-of-function screening in a human MCF10DCIS.COM cancer cells, PHGDH was identified as one of several genes necessary for the growth of tumor cells." (PMID 24318446, 2013). "Suppression of PHGDH in PHGDH high-expression cancer cell lines causes a strong decrease in cell proliferation, as well as a reduction in serine synthesis." (PMID 24318446, 2013). "PHGDH (phosphoglycerate dehydrogenase), a key enzyme in the serine biosynthesis pathway, is a known rate-limiting enzyme and has been associated with the growth and progression of various cancers." (PMID 40842627, 2025). "Consequently, heterogeneity of PHGDH expression is linked to enhanced aggressiveness in primary cancers." (PMID 38698089, 2024). "In cancer cells PHGDH upregulation could be driven by KRAS activating mutations, thus we tested whether such mechanism would also take place in CCA cells." (PMID 35619118, 2022). "When studied in combination, the inhibition of both PHGDH and p-mTOR in ECSLCs causes further augmentation of autophagy, and additionally promotes apoptosis, demonstrating the clinical applicability of PHGDH-based manipulations in cancer therapies." (PMID 30250195, 2018). "This promiscuity could be of special relevance in determining the role of PHGDH in certain cancer forms that depend on PHGDH activity (often associated with elevated PHGDH expression levels) beyond its role in serine synthesis." (PMID 29262655, 2017). "In this context our work shows for the first time the biochemical basis for this finding, by confirming the binding of α-KG to human PHGDH, consistent with the suggestion that PHGDH could effect this cancer-linked transformation in vivo." (PMID 29262655, 2017). "Interestingly, multiple proteins linked to known cancer-associated metabolic pathways, such as glycolysis, serine synthesis (PHGDH), glutamine consumption (GLS), were lower in the ERPR tumours." (PMID 26725330, 2016). "Because D-2HG has been implicated in the pathogenesis of some human cancers we examined whether N-terminally tagged PHGDH results in lower 2HG production than wild-type PHGDH in cells." (PMID 25926973, 2015). "Furthermore, while tagged PHGDH retains some ability to convert 3PG to PHP, the structural alterations caused by including an epitope tag disrupts the ability of PHGDH to sustain cancer cell proliferation." (PMID 25926973, 2015). "Loss of PHGDH cancer dependence may be due to α-KG level restored by other pathways, such as alanine aminotransferase." (PMID 24318446, 2013). "Studies have shown that lower PHGDH levels are linked to increased metastatic potential, as the downregulation of de novo serine biosynthesis may enhance the invasiveness of cancer cells by promoting reliance on exogenous serine and other metabolic adaptations." (PMID 40475404, 2025). "Importantly, inhibition of mTORC1 signaling alone exhibited effects similar to those of genetic or pharmacological blockade of PHGDH, while supplementation with αKG rescued the defects associated with PHGDH deficiency and restored the recruitment of macrophages to cancer cells." (PMID 38409249, 2024). "PHGDH exemplifies the complex interplay between metabolic reprogramming, oncogenic signaling, and therapeutic vulnerability in cancer biology." (PMID 41486146, 2026). "As the rate-limiting enzyme of de novo serine biosynthesis, PHGDH is a pivotal metabolic node frequently dysregulated in cancers." (PMID 41486146, 2026).
cancer (continued). "Cancer cells use PHGDH and NAD+ to oxidize 10% of the 3-phosphoglycerate (3-PG) produced by glycolysis into the serine precursor 3-phosphohydroxypyruvate (3-PPyr)." (PMID 40265021, 2025). "This silencing leads to PHGDH-mediated activation of the serine synthesis pathway that, in turn, supports cancer cell survival and proliferation in glucose depleted environments." (PMID 39761690, 2025). "For example, genomic and transcriptional analyses of cancer discovered that increased PHGDH expression promotes tumor growth and provides a proliferative advantage in serine depleted tumor microenvironments." (PMID 40654753, 2025). "In past years, a number of studies focused on the investigation of the effects due to PHGDH inhibition, especially on the metabolism of cancer cells related to decreased L-Ser levels." (PMID 40761926, 2025). "Previous studies have reported that SSP coordinates the nucleotide levels by maintaining the central carbon metabolism in cancer cells that express high PHGDH." (PMID 40662194, 2025). "Recent studies have highlighted the role of PHGDH modifications in promoting serine synthesis and their potential as therapeutic targets in cancer." (PMID 40368902, 2025). "PHGDH-mediated l-serine biosynthesis is crucial for cancer cells to survive the serine- and glycine-limited microenvironments." (PMID 40138393, 2025). "Recent studies indicate that activating the serine synthesis pathway (SSP) and upregulating PHGDH expression can promote the growth of various cancer subtypes." (PMID 40265021, 2025). "PHGDH is critical for L-serine biosynthesis, and its high expression in diseases, such as cancers, increase the throughput of serine synthesis." (PMID 40078876, 2025). "It is noteworthy that although PHGDH is often amplified in various types of cancer, therapeutic interventions targeting PHGDH are far more complex than initially imagined." (PMID 40265021, 2025). "These transporters, as well as enzymes such as glutaminase (GLS) and phosphoglycerate dehydrogenase (PHGDH), contribute to the metabolic flexibility and adaptability of cancer cells, allowing them to thrive in nutrient-deficient tumor microenvironments." (PMID 39973065, 2025). "Amino acid analysis in advanced tumors can guide the application of novel therapies, such as PHGDH inhibitors for serine-dependent cancers or targeting asparagine metabolism to reduce metastatic spread." (PMID 39973065, 2025). "This dual role of PHGDH in different cancers presents a paradox that remains unresolved and highlights the need for a deeper understanding of the regulatory mechanisms that govern serine metabolism along with dependency on serine uptake in cancer." (PMID 40475404, 2025). "NCT-503 effectively inhibits PHGDH activity, thereby blocking the serine synthesis pathway, which in turn affects cancer cell growth and survival." (PMID 40989165, 2025). "Conversely, cancers harboring mutations or dysregulated expression of SSP enzymes (e.g., PHGDH) display compromised biosynthetic capacity, leading to heightened reliance on exogenous serine uptake." (PMID 40265021, 2025). "Phosphoglycerate dehydrogenase (PHGDH), a crucial enzyme in the de novo serine synthesis pathway (SSP), is implicated in tumorigenesis and therapy resistance across various cancers." (PMID 40102981, 2025). "PHGDH levels are increased in different types of cancers and correlate with tumor malignancy; indeed, many cancer cells are dependent on Ser availability, and PHGDH inhibition impairs tumor cell growth in vitro and in vivo." (PMID 40640948, 2025). "3-phosphoglycerate generated from glycolysis in cancer cells is oxidized by PHGDH (phosphoglycerate dehydrogenase) to 3-phosphohydroxypyruvate, a precursor for de novo serine synthesis." (PMID 40034230, 2025). "PHGDH is universally expressed in all organisms and overexpressed in various metabolic diseases, especially in cancer." (PMID 40598535, 2025).